ABCG2 (ATP binding cassette subfamily G member 2 (JR blood group))
Diseases named in the same sentence as ABCG2 in open-access papers (continued):
Sharing a sentence is not in itself a finding about the gene and the disease.
tumor (continued). "In vivo, we found that the combination of topotecan with the well-tolerated Ko143, a dual inhibitor of ABCB1 and ABCG2, reduced tumor growth by more than 240% compared to single agents treatment, translating to an increase in survival from 17 to 28 days." (PMID 29186899, 2017). "In the multivariable analysis, besides Fuhrman grade, the ABCG2 expression was an independent prognostic marker for overall survival (p < 0.001) when incorporating other relevant tumor and clinical parameters (HR = 3.84, 95% CI: 1.92–7.70)." (PMID 28347288, 2017). "This study revealed intra-tumor heterogeneity of ABCG2 immunostaining in tissue samples from some CRC patients." (PMID 27257141, 2016). "At present, no universally accepted guidelines exist for the analytical or clinical validation of ABCG2 in clinical tumor tissues." (PMID 27257141, 2016). "ABCG2 was described for the first time in tumour cells, where it produced a significant resistance to chemotherapeutic agents." (PMID 26578453, 2016). "In contrast, the promoters of ABCB1 and ABCG2 were found to be methylated in ≥ 75% of the tumor tissues." (PMID 27689338, 2016). "Here, we provide the necessary analytical evidence for the use of mAb BXP-21 to detect and semi-quantitatively assess the ABCG2 protein in FFPE tumor tissue." (PMID 27257141, 2016). "The LNCaP-CRPC cells have also acquired some phenotypic CSC markers including CD44, α2β1, and ABCG2, all of which have been shown by us to enrich for tumor-initiating and tumor-propagating cells in different PCa models." (PMID 26871947, 2016). "Using the MTT cell viability assay in vitro, we observed that cotreatment with BDNF clearly enhanced the chemosensitivity of NCI-H69 tumor cells to Cisplatin and induced the downregulation of ABCG2." (PMID 27852063, 2016). "With the exception of CpG7, the CpGs targeted in the ABCG2 promoter were methylated (methylation status ≥ 5%) in at least 14 out of the 16 tumor, tumor-adjacent and tumor-distant tissues." (PMID 27689338, 2016). "The tumor size of SW480 cells was significantly smaller in the group treated with PPa-PDT compared to the SW480/ABCG2 injected group." (PMID 26149077, 2015). "ABCG2-siRNA-loaded PEAL NPs + UTMD significantly suppressed the expression of the target gene in tumor xenografts, consistent with the gene silencing effects observed in vitro." (PMID 26575421, 2015). "ATP-binding cassette subfamily G member 2 (ABCG2), a chemotherapy resistance-related molecule, is strongly expressed in NSCs and tumor stem cells (TSCs) but is commonly inactive in further matured cells." (PMID 26563263, 2015). "The tumor growth rate of the xenograft mice implanted with ABCG2 overexpressing cells was significantly reduced in the A-803467-topotecan combination group as compared to the vehicle, A-803467 alone, and topotecan alone groups." (PMID 26515463, 2015). "Increased ALA-PpIX accumulation in various tumor cell lines by inhibiting PpIX efflux has been demonstrated with ABCG2 inhibitors fumitremorgin C and its less toxic and more selective analog Ko143." (PMID 26516850, 2015). "Tumor growth was significantly suppressed in the group infected with ABCG2 siRNA relative to the group infected with control siRNA." (PMID 26517090, 2015). "Consistently, ABCG2-positive staining localized in membrane and/or cytoplasm and was found to be much stronger in the tumor tissues formed by the SOX4-overexpressing CaSki cells than that in the tumors formed by the control cells." (PMID 26583330, 2015). "Here, the device was also used to study tumor heterogeneity, the differences on growth rate, sensitivity to indomethacin and ABCG2 protein expression level between the two types of MHCC 97L clones were further examined in this work." (PMID 26149707, 2015). "ENPP1 induced the generation of a SP fraction that had tumour seeding ability and was resistant to conventional chemotherapy by promoting the expression and cell surface localization of ABCG2." (PMID 26065921, 2015).
tumor (continued). "Among the 3 single surface marker (ABCG2, CD44, and α2β1) profiles, the ABCG2+ Du145 cell population (from either cultures or xenografts) manifested significantly higher tumor-regenerating activity than the ABCG2− population." (PMID 26246472, 2015). "The tumor doubling time was 3.6 days (control siRNA) and 6.6 days (ABCG2 siRNA), and the tumor inhibition rate on day 22 was 64.8% for the group treated with ABCG2 siRNA." (PMID 26517090, 2015). "The RT-PCR technique was used in the four groups of nude mice to detect the mRNA expression of HIF-2α, ABCG2 and Oct-4 in the tumor tissue after 14 days of treatment." (PMID 25452783, 2015). "The in vivo study results indicated that A-803467 in combination with topotecan, significantly decreased the tumor growth in mice implanted with ABCG2 overexpressing H460/MX20 cells." (PMID 26515463, 2015). "Parental H460 cells and drug resistant ABCG2 overexpressing H460/MX20 cells were implanted into athymic nude mice to create xenograft tumor models to analyze the efficacy of A-803467 to circumvent resistance to topotecan in vivo." (PMID 26515463, 2015). "The western blotting technique was used to detect the protein expression of HIF-2α, ABCG2 and Oct-4 in the tumor tissue after 14 days of treatment." (PMID 25452783, 2015). "We also found in LMNA-KD-derived tumor spheres a marked increase in the expression of the ABC membrane transporter gene ABCG2." (PMID 26439802, 2015). "High expression of ABCG2 and/or P-gp did not result in FL118 resistance in cell culture, and FL118 was able to inhibit tumor growth better than irinotecan in xenograft models that expressed high levels of ABCG2." (PMID 26714461, 2015). "The HIF-2α, ABCG2 and Oct-4 protein expression in the tumor tissue was significantly decreased in the celecoxib and combination treatment groups compared with the control and 5-Fu groups." (PMID 25452783, 2015). "Tumor cell heterogeneity on cell morphology, growth rate, drug sensitivity and ABCG2 protein expression difference have been conducted at single cell clone level on the device." (PMID 26149707, 2015). "The results showed that the HIF-2, ABCG2 and Oct-4 protein expression levels in the tumor tissue were high in the control group, and were further increased in the 5-Fu group." (PMID 25452783, 2015). "The results revealed that ISL exerted synergistic effects with epirubicin and induced autophagy in vivo, indicated by increased LC3-II and decreased ABCG2 expression in tumor tissues." (PMID 25026296, 2014). "We also noticed that most cells overlaid with ABCG2 and Ki-67 were mainly found in the same location of the tumor tissue." (PMID 24804195, 2014). "V-BCRPi injection into tumor histiocytes followed by mRNA and protein level analysis showed that BCRP/ABCG2 expression was inhibited." (PMID 25076217, 2014). "ABCG2 can be expressed in stem cells isolated from both normal and tumor tissues, which further indicates its essential role in stem cell biology." (PMID 24804195, 2014). "Immunohistochemical analysis showed that ABCG2 was expressed ubiquitously in normal and tumor tissues." (PMID 24804195, 2014). "ABCG2/BCRP1 is a transmembrane protein that plays an important role in the multidrug resistance (MDR) of tumor cells." (PMID 24418020, 2014). "We also developed an inhibition model of tumor growth predicting tumor growth dynamics, to be used as a template to design studies for producing more efficient ABCG2 inhibitors." (PMID 25474134, 2014). "In light of ABCG2-positive tumor sensitization and as required by preclinical development, we decided to define the pharmacokinetics parameters of MBL-II-141 and its possible interactions on CPT11 and SN-38 pharmacokinetics." (PMID 25474134, 2014). "There was evidence that ATP-binding cassette sub-family G member 2 (ABCG2) and Vacuolar-H + -ATPase (V-ATPase) were associated with pathological grade, TNM stage and tumor metastasis in esophageal squamous cancer cells." (PMID 25030066, 2014).
tumor (continued). "Very recently, telatinib (15 mg/kg) in combination with doxorubicin (1.8 mg/kg) was shown to significantly decrease the growth rate and tumor size of ABCG2-overexpressing tumors in a xenografted nude mouse model." (PMID 25474134, 2014). "Our results found that the combination of Icotinib with topotecan markedly enhanced antitumor activity of topotecan in the ABCG2-overexpressing NCI-H460/MX20 tumor xenografts model when compared to either the Icotinib or topotecan treatment alone." (PMID 24980828, 2014). "Our results are in agreement with the findings of Patrawala and colleagues who found that, in several tumor cell lines, 1% of the ABCG2+ dividing cells segregated asymmetrically." (PMID 25216750, 2014). "After injecting V-BCRPi-infected JAR tumor cells into the dorsal skin of hairless mice, BCRP/ABCG2 expression in the tumor tissue was determined using immunohistochemistry, fluorescent quantitative RT-PCR and Western blot analyses." (PMID 25076217, 2014). "The CSCs are spared by their high expression of multidrug transporters (especially, ABCG2), mediating their chemoresistance, and eventually lead to tumor relapse and metastasis." (PMID 25436978, 2014). "Determining how to improve the drug sensitivity of BCRP/ABCG2 in selected RNAi-targeted tumor cells still remains to be elucidated." (PMID 25076217, 2014). "The values of ABCG2 band density to β-actin band density in control tumor tissues and 5% ethanol-treated tumor tissues were 1.09 ± 0.16 vs. 1.12 ± 0.20, p > 0.05." (PMID 24009622, 2013). "We found that SOX2 is expressed at high level in SP/ALDHBr cells, and knockdown of SOX2 suppressed the expressions of ALDH1A1 and ABCG2, and suppressed tumor-initiation." (PMID 23967051, 2013). "Our study also showed that ABCG2 expression in tumor tissue correlated with a tendency of a higher Ki67 index, which is a well-established marker of proliferation." (PMID 24194752, 2013). "The conserved expression of ABCG2 in stem cells from both normal tissue and tumor tissues again indicates its important role in stem cell biology." (PMID 24194752, 2013). "We believe that the dynamic change of ABCG2 during different stages of tumor development is worth studying." (PMID 24194752, 2013). "The tumor-protective properties of ABCG2 expression are reported to be a feature of a subset of stem cell-like tumor cells." (PMID 23467750, 2013). "Despite the difference of tumorigenicity, tumor sizes were similar between ABCG2+ and ABCG2− groups." (PMID 24194752, 2013). "Previous studies revealed that ABCG2 is expressed in a variety of tumor cells and human solid tumors." (PMID 24179544, 2013). "Following the staging criteria of stain intensity (SI), the average SI score of ABCG2 expression in LMWH treated tumor tissues was 3.63 compared with the average SI score of 9.13 in control tumor tissues (3.63±1.69 vs 9.13±2.03, p<0.05)." (PMID 22844424, 2012). "The individual expression of CD44, CD24, ABCG2, and EpCAM in primary tumor samples ranged from 19% to 64%, 15% to 77%, 2% to 7%, 4% to 65%, respectively." (PMID 22328825, 2012). "We also evaluated tumor-specific ABCG2 inhibition by Ko143 in Abcg2−/− host animals that carried tumors with topotecan-induced ABCG2 expression." (PMID 23028879, 2012). "Although tumor-specific ABCG2 inhibition by Ko143 resulted in improved overall survival of tumor-bearing animals, the benefit was rather modest." (PMID 23028879, 2012). "Immunohistochemistry analyses consistently showed that LMWH significantly reduces ABCG2 protein expression in LMWH-treated tumor tissues compared with controls." (PMID 22844424, 2012). "In the present study, we found HIF-2α expression was correlated with ABCG2 expression significantly (p = 0.001) in paraffin-embedded tumor samples using the IHC method." (PMID 22452996, 2012). "The co-expression of EpCAM+CD44+, EpCAM+CD24+, and EpCAM+ABCG2+ ranged from 0.83% to 42.6%, 0.65% to 41.4%, and 1.6% to 6.5%, respectively, in the eight RB tumor samples." (PMID 22328825, 2012).
tumor (continued). "Like topotecan, the topoisomerase I inhibitor SN38 is an ABCG2 substrate, and therefore drug-naïve tumors with ABCG2-positive nests of tumor cells should quickly acquire resistance during irinotecan treatment." (PMID 23028879, 2012). "The protein expression of ABCG2 in tumor tissues of LMWH treated mice were significantly lower than those in control mice (30.38% ±2.13% vs 20.22% ±2.01%, p<0.05)." (PMID 22844424, 2012). "Among the various conditions within the tumor microenvironment, hypoxia has been demonstrated to upregulate ABCG2 in a mouse progenitor cell model." (PMID 22778999, 2012). "Consistently, immunohistochemistry stainings of ABCG2 in LMWH-treated tumor tissues were significantly reduced compared with those in controls." (PMID 22844424, 2012). "This study investigated the upregulation of ABCG2 by these adverse growth conditions within the tumor microenvironment." (PMID 22778999, 2012). "Significantly low level of expression of ABCG2 was observed in LMWH treated tumor tissues compared with controls." (PMID 22844424, 2012). "ABCB1 (P-glycoprotein, P-gp, MDR1), ABCC1-C6 (MRP1-6) and ABCG2 (BCRP) confer resistance to cytostatic drugs of tumors and contribute to the failure of tumor." (PMID 22590507, 2012). "This study aims to evaluate the regulation of ABCG2 in response to a few characteristic growth conditions within the tumor microenvironment, including hypoxia, glucose deprivation, and low pH." (PMID 22778999, 2012). "Numerous studies documented that overexpression of ABCG2 correlates with higher migration and invasion in a variety of different tumor types." (PMID 22952907, 2012). "Others have shown that ABCG2 expression plays an important role in tumor stem cell proliferation, maintenance of stem cell phenotype and promotion of tumor cell development." (PMID 23244569, 2012). "Tumour-specific ablation of Abcg2 (the gene coding for BCRP) significantly reduced tumour growth and increased overall survival of topotecan treated animals." (PMID 22332018, 2011). "In general, the SP of D121 tumour cells is 1.8%, which displayed elevated expression of the ABCG2-ATP-binding cassette transporters on the cell surface, indicative of resistance to multiple chemotherapeutic drugs." (PMID 21468047, 2011). "The clinical correlation between BCRP/ABCG2 expression in tumor lesions and poor outcome was also observed in wtEGFR-expressing NSCLC patients who received gefitinib treatment." (PMID 21731744, 2011). "Later, tumor initiating cells were identified in the SP, as indicated by ABC transporter gene expression (ABCB1 or ABCG2), chemo-resistance or tumorigenicity in vivo." (PMID 20836839, 2010). "LMP2A, Bmi-1 and ABCG2 transcripts were found to be low or undetectable in the 15 inflammatory samples but extremely high in the NPC tumor tissue." (PMID 20532215, 2010). "The ABCG2/BCRP1 gene was first isolated from human tumour cell lines, in which it was involved in drug resistance." (PMID 20354527, 2010). "Single cell suspensions were obtained from all tumor xenografts and analyzed after one to two passage by means of flow cytometry to detect ABCG2-expressing cells." (PMID 21203549, 2010). "Like IGR39 cells sorted based on CXCR6 expression alone, tumors from IGR39 ABCG2+/CXCR6+ cells required only 21 days for tumor detection." (PMID 21203549, 2010). "ABCB1 (P-glycoprotein, P-gp, MDR1), ABCC1-C6 (MRP1-6) and ABCG2 (BCRP) confer resistance to cytostatic drugs of tumors and contribute to the failure of tumor chemotherapy." (PMID 20428086, 2010). "ABCB1 (P-glycoprotein, MDR1), ABCC1-C6 (MRP1-6) and ABCG2 (BCRP) confer resistance to cytostatic drugs of tumors and contribute to the failure of tumor chemotherapy." (PMID 17726528, 2007). "Members of the ATP-binding cassette superfamily of proteins (ABCB1 and ABCG2) function to export irinotecan from tumour cells, while drug metabolism via the cytochrome P450 system (CYP3A4) or glucuronidation (UGT1A1) can also occur." (PMID 15655543, 2005).